NSD1 (nuclear receptor binding SET domain protein 1)
Diseases named in the same sentence as NSD1 in open-access papers (continued):
Sharing a sentence is not in itself a finding about the gene and the disease.
Sotos syndrome (continued). "Supporting this, it has been reported that NSD1+/− Sotos syndrome patients exhibit a specific and reproducible DNA methylation signature." (PMID 31575610, 2019). "More than 75% of the cases with Sotos syndrome are due to intragenic mutations and deletions of the nuclear receptor binding SET-Domain 1 (NSD1) which is located at chromosome 5q35." (PMID 30873120, 2019). "Our studies additionally defined phenotype-related accelerated and decelerated epigenetic aging in two histone methyltransferase disorders: NSD1 Sotos syndrome overgrowth disorder and KMT2D Kabuki syndrome growth impairment." (PMID 31160375, 2019). "“Pericentric inversion” (VariO:0201) includes the centromere, as an example leading to disruption of the NSD1 (nuclear receptor binding SET domain protein 1) gene in Sotos syndrome." (PMID 30591019, 2018). "The Sotos syndrome overlap index increased with increasing number of inactivating NSD1 lesions in both HNSC and LUSC, and was higher in the NSD1 DNA methylation subtype compared with other subtypes in HNSC, though not in LUSC (Supplementary 6b)." (PMID 29213088, 2017). "Our studies also found NSD1 expression to be profound in human fetal brain and cerebellum, accounting for prenatal onset and hypoplasia of cerebellar vermis seen in Sotos syndrome." (PMID 27834868, 2016). "In this study, we report two patients with distinct overgrowth syndromes, Malan syndrome (19p13.2 deletion of NFIX) and Sotos Syndrome (5q35.2 deletion of NSD1)." (PMID 27688808, 2016). "The germline abrogation in NSD1 results in a childhood overgrowth syndrome called Sotos syndrome (OMIM 117550)." (PMID 27187383, 2016). "The connection between NSD1 and DNA hypomethylation is likely related to a loss of its histone H3K36 methyltransferase activity that is a documented event in Sotos syndrome." (PMID 25960768, 2015). "Constitutional mutations in two different genes involved in regulating histone modifications, NSD1 and EZH2, have been shown to cause clinically overlapping overgrowth disorders, Sotos syndrome (SS) and Weaver syndrome, respectively." (PMID 26690673, 2015). "Mutations and deletions in NSD1, an HMT closely related to MMSET, are implicated in Sotos syndrome, a disorder characterized by developmental overgrowth and cognitive disabilities." (PMID 25188243, 2014). "Although a large degree of phenotypic overlap exists between Sotos syndrome and Weaver syndrome, NSD1 and EZH2 regulate different methylation sites." (PMID 25750614, 2014). "Overgrowth disorders, Sotos syndrome and Weaver syndrome, are caused by heterozygous mutations in the HMT NSD1 (Sotos and Weaver syndromes) and EZH2 (Weaver syndrome)." (PMID 25750614, 2014). "This was demonstrated by engineering mutations into PHD fingers 2 and 3 analogous to those found in NSD1 in Sotos syndrome patients." (PMID 25188243, 2014). "In case 10, we identified a micro deletion of the 5q35 region including the NSD1 gene in one Korean patient with Sotos syndrome." (PMID 21549014, 2011). "We therefore believe that a diagnosis of Weaver syndrome should be given only if the presence of NSD1 abnormalities has been excluded, otherwise it is labeled as Sotos syndrome." (PMID 20407649, 2009). "No biochemical or endocrinological markers have been documented in patients with Sotos syndrome and/or NSD1 aberrations, especially endocrine and paracrine systems." (PMID 17825104, 2007). "The identification of NSD1 has been a major step in the history of Sotos syndrome and has opened a new area in the elucidation of this condition." (PMID 17825104, 2007). "Based on the clinical presentation, a suspicion of Sotos syndrome was raised and subsequently confirmed by genetic analysis (MLPA P245), identifying a pathogenic variant in the NSD1 gene (deletion of two markers for NSD1 gene)." (PMID 41303235, 2025). "Sotos syndrome is associated with a wide range of intragenic variants and deletions of the NSD1 gene, though genotype–phenotype associations are not prominent." (PMID 41153407, 2025).
Sotos syndrome (continued). "Although all Sotos syndrome patients should be monitored for scoliosis, recent research emphasized that patients with NSD1 microdeletions have a higher probability of scoliosis development and progression, which may require early intervention." (PMID 38673476, 2024). "However, subsequent reports on several patients with Sotos syndrome and CHI who carried intragenic NSD1 mutations rather suggest that the defect in NSD1 itself is sufficient to cause CHI." (PMID 37065762, 2023). "The pathogenesis of this condition is unknown, but the potential metabolic role that NSD1 plays in both Sotos syndrome and OA should be studied." (PMID 36983761, 2023). "In contrast to the Nsd1 mutant mice that does not show an enlarged head circumference, loss of function mutation in Apc2 resulted in a Sotos Syndrome-like phenotype in mice, with increased head circumference and dilated brain ventricles." (PMID 36845425, 2023). "The nonsense mutation c.6095G>A (p.TRP2032*) in NSD1 gene associated with Sotos syndrome has not been reported before." (PMID 37908045, 2023). "In conclusion, we propose that NSD1 may participate in Sotos syndrome’s mechanism of action by regulating the function of lncRNA, inducing the down-expression of GSC, NDRG2 and SORBS1 and the up-expression of SFN and ZNF883." (PMID 35888078, 2022). "Finally, ccRCC tumor samples harboring epigenetic silencing of NSD1 displayed a specific genome-wide DNA methylation pattern consistent with the methylome signature observed in Sotos syndrome and HNSCC." (PMID 36230787, 2022). "Interestingly, where these candidate genes have been identified, they are predominantly involved in epigenetic regulation including chromatin remodeling or histone modification, e.g., CREBBP in Rubinstein–Taybi syndrome and NSD1 in Sotos syndrome." (PMID 35887210, 2022). "Finally, we also analyzed Sotos Syndrome (MIM# 117550), an overgrowth syndrome caused by truncating and missense mutation in the nuclear receptor binding SET domain protein 1 (NSD1) gene." (PMID 36064314, 2022). "Likewise, a NSD1 DNA hypomethylation signature that overlaps with the Sotos syndrome hypomethylation signature was observed in glioma and neuroblastoma." (PMID 36230787, 2022). "While most cases of Sotos syndrome in non-Japanese patients are caused by intragenic variants of NSD1, almost half of the cases in Japanese patients are caused by 5q35 microdeletions encompassing NSD11." (PMID 36379925, 2022). "In contrast, for several other genes (e.g., FGFR3 and NSD1) a loss of function is associated with tall stature (CATSHL syndrome and Sotos syndrome, respectively), and gain of function with short stature (FGFR3 and CDKN1C; Achondroplasia and Silver-Russell syndrome)." (PMID 34194391, 2021). "Here we report two Sotos syndrome patients arising from entire NSD1 deletion that have CVDs." (PMID 34031356, 2021). "Interestingly, microduplications of 5q35.2–q35.3 encompassing the NSD1 gene locus have been reported in rare patients with a clinically reversed SOTOS syndrome." (PMID 34575025, 2021). "Our results suggest that NSD1 abnormalities can be identified in unexpected situations, particularly in individuals with cerebrovascular diseases in early infantile periods or in adult patients whose Sotos syndrome was unnoticed." (PMID 34031356, 2021). "Germline heterozygous mutations in the genes encoding core PRC2 members (EZH2, EED and SUZ12), NSD1 and DNMT3A have been implicated in a triad of highly phenotypically related human developmental disorders: Weaver syndrome, Sotos syndrome and Tatton-Brown–Rahman syndrome, respectively." (PMID 31575610, 2019). "Furthermore, in vitro assays have determined that the H36 methyltransferase activity of NSD1 is impaired in Sotos syndrome-mutant versions of the enzyme." (PMID 31575610, 2019).
Sotos syndrome (continued). "Sotos syndrome (SoS) is characterized by overgrowth of prenatal onset, learning disability, and characteristic facial appearance; it is usually due to haploinsufficiency of NSD1 gene at chromosome 5q35." (PMID 29164086, 2017). "Median levels of the Sotos syndrome overlap index, but not the random overlap index, increased incrementally with and increasing number of inactivating NSD1 lesions (Mutations and deletions) in both HNSC and LUSC." (PMID 29213088, 2017). "Sotos syndrome is caused by intragenic mutations or microdeletions of the NSD1 gene, resulting in loss of function and it has been suggested that abnormalities of the NSD1 gene are present in more than 90 % of individuals with a clinical diagnosis of Sotos syndrome." (PMID 27771801, 2017). "Since NSD1 mutations have not been detected in 7%–30% of Sotos patients, other genes were also screened in some cases of unexplained Sotos syndrome." (PMID 27834868, 2016). "More than 80% of patients with Sotos syndrome carry NSD1 mutations, whereas for 20% of phenotypically characterized cases with Sotos syndrome underlying aberrations in the NSD1 gene have not been detected." (PMID 27834868, 2016). "Haploinsufficiency of the human 5q35 region spanning the NSD1 gene results in a rare genomic disorder known as Sotos syndrome (Sotos), with patients displaying a variety of clinical features, including pre- and postnatal overgrowth, intellectual disability, and urinary/renal abnormalities." (PMID 22926222, 2012). "Sotos syndrome has been described in a number of patients with autism spectrum disorders, suggesting that NSD1 could be involved in other cases of autism and macrocephaly." (PMID 18001468, 2007). "The description of several cases of Sotos syndrome in patients with autism and macrocephaly suggests that NSD1 could be involved in other cases of autism." (PMID 18001468, 2007). "Our results showed no point mutations or deletions of NSD1, indicating that Sotos syndrome is a rare cause of autism spectrum disorders with macrocephaly." (PMID 18001468, 2007). "Point mutations are identified in the majority of non-Japanese patients with Sotos syndrome (~80%), whereas 5q35 microdeletions encompassing NSD1 are the major cause among Japanese patients (>50%)." (PMID 18001468, 2007). "Our findings suggest that Sotos syndrome is a rare cause of autism spectrum disorders and that screening for NSD1 mutations and deletions in patients with autism and macrocephaly is not warranted in the absence of other features of Sotos syndrome." (PMID 18001468, 2007). "Sotos syndrome is a non-progressive neurologic disorder caused by NSD1 deletions or mutations." (PMID 38050304, 2023). "In the same vein, in human colon cancer cell line HCT116, NSD1 has been reported to bind to the promoter proximal regions of a panel of genes, some, such as bone morphogenetic protein 4, may mediate its role in cancer and Sotos syndrome." (PMID 36230787, 2022). "However, as Sotos syndrome has a genetic cause, it is important to establish the prevalence of ASD within this population in order to determine whether the NSD1 gene could be implicated in ASD." (PMID 27771801, 2017). "Therefore, these NSD1 mutation-negative families will surely contribute to the identification of new genes involved in Sotos syndrome in the future." (PMID 27834868, 2016). "However, our findings suggest the possibility that NSD1 exon 3 deletions might be associated with an atypical phenotype that includes the neurodevelopmental and some medical features of Sotos syndrome, but not the characteristic facial features or overgrowth." (PMID 41153407, 2025). "By analogy with Sotos syndrome, we propose that in malignant melanomas, APC operates downstream NSD1." (PMID 36230787, 2022). "Both NSD1 and NSD2 haploinsufficiency lead to neurodevelopmental syndromes, namely Sotos syndrome and WHS, respectively." (PMID 31998360, 2019).
Sotos syndrome (continued). "However, recent studies have shown that HC and height are normal in 10% of NSD1 mutation-positive patients, indicating that overgrowth, previously considered as a major criterion of the disorder, is not necessary for the diagnosis of Sotos syndrome." (PMID 18001468, 2007). "We did not detect any CNVs encompassing the NSD1 gene at chr5q35, which would have been consistent with Sotos syndrome." (PMID 40041288, 2025). "NSD1-altered HNSCC and LUSC correlated at the DNA methylation and gene expression levels, featuring ectopic expression of developmental transcription factors and genes that are also hypomethylated in SOTOS syndrome." (PMID 34575025, 2021). "Nuclear receptor SET domain-containing protein-1 (NSD1) silencing by epigenetic modification leads to Sotos syndrome, as well as nonhereditary neuroblastoma and glioma development." (PMID 33402862, 2020). "Due to phenotypic presentation with macrosomia, Sotos Syndrome was considered in the differential diagnosis, but genetic testing did not detect any aberrations in the NSD1 gene." (PMID 32722525, 2020). "Because of their high sequence similarities with NSD1, both the NSD2 and NSD3 genes were tested previously as potential candidates for NSD1-negative Sotos syndrome cases." (PMID 27834868, 2016). "The literature on Sotos syndrome, before the identification of the NSD1 gene responsibility, has to be read carefully since it is mixed with publications that evidently do not deal with the Sotos syndrome." (PMID 17825104, 2007). "NSD1 is not known to be directly involved in regulating insulin secretion but patients with Sotos syndrome have alterations in the IGF-1 axis which could play a role in β-cell hyperplasia." (PMID 30873120, 2019). "However, 7 to 35% of the patients with Sotos syndrome of the reported series did not have any NSD1 anomalies as in the reported case." (PMID 31470900, 2019).
acute myeloid leukemia (28 papers, 2012 to 2025). Acute myeloid leukemia (AML) is a group of neoplasms arising from precursor cells committed to the myeloid cell-line differentiation. "NSD1′s loss has been reported to be involved in a rare form of acute myeloid leukemia called acute erythroleukemia, which is generally associated with poor outcome." (PMID 36230787, 2022). "NSD1 is associated with the development of acute myeloid leukemia (AML), head and neck squamous cell carcinoma, neuroblastoma and glioma." (PMID 36532012, 2022). "NSD1 mutations have been implicated in the pathogenesis of acute myeloid leukemia, HPV-negative head and neck squamous cell carcinoma, hepatocellular carcinoma and colorectal carcinoma." (PMID 36611369, 2022). "NSD1 is expressed in the human brain and has been implicated in prostate cancer, childhood acute myeloid leukemia and Sotos syndrome." (PMID 34127790, 2021). "This protein is encoded by NSD1 gene and plays a pivotal role in childhood acute myeloid leukemia (AML)." (PMID 30303964, 2018). "Acute myeloid leukemia is prioritized as the most significant m6A associated disease, where m6A-regulated genes NSD1, PICALM, and ABL2 are OMIM-annotated disease genes, suggesting that they may be potential m6A-associated biomarkers in leukemia." (PMID 30601803, 2019). "NSD1 gene fusion is strongly associated with poor prognosis in pediatric acute myeloid leukemia." (PMID 31727171, 2019). "NSD1 haploinsufficiency and point mutations are implicated in Sotos syndrome, a childhood developmental disease, prostate cancer, melanoma, and acute myeloid leukemia (AML)." (PMID 38256018, 2024). "In contrast, in acute myeloid leukemia, a recurring translocation that fuses NSD1 to nucleoporin-98 (NUP98) leads to leukemogenesis through dysregulated H3K36 methylation at certain genetic loci." (PMID 31321084, 2019). "NSD1 has been linked to several cancers, including multiple myeloma and lung cancer, and translocations involving NSD1 and NUP98 have been identified in childhood acute myeloid leukemia." (PMID 24874471, 2014). "To demonstrate the utility of our in-house developed qRT-PCR assay to detect the presence of NUP98::NSD1 oncogenic fusion in patients, we screened 150 acute myeloid leukemia (AML) patients." (PMID 36553008, 2022). "NSD1, a close homologue of MMSET, is fused to the NUP98 locus in rare cases of acute myeloid leukemia creating the NUP98-NSD1 fusion protein." (PMID 25188243, 2014). "Furthermore, translocations involving NSD1 have been found in patients with acute myeloid leukemia (AML) and breast cancer, indicating that NSD1 may function in the regulation of multiple downstream genes involved in various processes, such as bone morphogenesis, development and cancer." (PMID 27834868, 2016).
Weaver syndrome (21 papers, 2005 to 2025). Weaver syndrome (WVS) is a rare, multisystem disorder characterized by tall stature, a typical facial appearance (hypertelorism, retrognathia) and variable intellectual disability. "By interrogating DNAm in SS patients, we identify a genome-wide, highly significant NSD1+/−-specific signature that differentiates pathogenic NSD1 mutations from controls, benign NSD1 variants and the clinically overlapping Weaver syndrome." (PMID 26690673, 2015). "To further assess the specificity of the NSD1+/−-specific signature, we used it to analyse the DNAm profiles of eight patients with a clinical diagnosis of Weaver syndrome (OMIM 277590) and confirmed mutations in EZH2 (refs 10, 11)." (PMID 26690673, 2015). "There are some reports of NSD-1 mutations in individuals with Sotos and Weaver syndromes and more recently mutations in the EZH2 gene in three families with Weaver syndrome have been identified." (PMID 25009745, 2014). "Recently, NSD1 mutations have been found in some cases of Weaver syndrome patients arguing for allelic heterogeneity." (PMID 15904506, 2005). "The Sotos and Weaver syndromes, overgrowth syndromes produced by germline mutations in the NSD1 and EZH2 genes, respectively, encode histone methyltransferases and have considerable clinical overlap with MC, giving rise to a high, broad forehead, and prominent chin." (PMID 38791606, 2024). "Likewise, NSD1 is associated with Sotos and Weaver syndrome and only in specific exons." (PMID 36550402, 2022). "In some overgrowth syndromes, variants in epigenetic regulators are associated with disease occurrence, such as variants of histone methyltransferases NSD1 in Sotos syndrome and EZH2 in Weaver syndrome." (PMID 38791606, 2024). "A Weaver syndrome-associated mutation affecting the H3K36-sensing pocket in EZH2 is also reported to disrupt the crosstalk between PRC2 and NSD1 on chromatin." (PMID 31575610, 2019). "Again, this result is consistent with a model of disturbed crosstalk between PRC2 and NSD1 as a feature of Weaver syndrome." (PMID 31575610, 2019). "For neurobehavioral diseases, Soto and Weaver syndromes were predicted with low p-values via the nuclear receptor binding SET domain protein 1 based on OMIM data for all three substances." (PMID 21846611, 2011).
leukemia (18 papers, 2013 to 2025). A malignant (clonal) hematologic disorder, involving hematopoietic stem cells and characterized by the presence of primitive or atypical myeloid or lymphoid cells in the bone marrow and the blood. "For example, translocations involved the H3K36 methyltransferase Nsd1 are linked to leukemias, whereas activating point mutations in the H3K27 methyltransferase Ezh2 are linked to B cell lymphoma." (PMID 23520493, 2013). "In the context of malignancy, translocations involving NSD1 have been identified in pediatric leukemias." (PMID 27213592, 2016). "In contrast, the frequently observed T1150A in NSD2 and its T2029A counterpart in NSD1, both observed in leukemia, are hyperactive and introduce up to three methyl groups in H3K36 in biochemical and cellular assays, while wildtype NSD2 and NSD1 only introduce up to two methyl groups." (PMID 37150325, 2023).